SAG (S-antigen visual arrestin)
Description:
Binds to photoactivated, phosphorylated RHO and terminates RHO signaling via G proteins by competing with G proteins for the same binding site on RHO (By similarity). May play a role in preventing light-dependent degeneration of retinal photoreceptor cells.
Synonyms: S-AG; ARRESTIN; RP47; RP96
Tractability: Antibody: UniProt places it where antibodies can reach, with medium confidence.
Gene: Protein-coding gene on chromosome 2 (233,307,816 to 233,347,055, forward strand). Ensembl gene ENSG00000130561.
Subcellular location: Cell projection, cilium, photoreceptor outer segment; Membrane
Pathways (Reactome):
Sensory Perception: Activation of the phototransduction cascade; Inactivation, recovery and regulation of the phototransduction cascade
Gene Ontology:
Molecular function: protein binding; G protein-coupled receptor binding; protein phosphatase inhibitor activity; opsin binding; phosphoprotein binding; spectrin binding
Biological process: cell surface receptor signaling pathway; G protein-coupled opsin signaling pathway; G protein-coupled receptor internalization; sensory perception; signal transduction
Cellular component: photoreceptor outer segment; cytosol; membrane; photoreceptor inner segment
Genetic constraint (gnomAD): Loss-of-function variants: 23 observed, 35.32 expected, observed/expected ratio (o/e) 0.65, 90% interval 0.47 to 0.92. The upper end of that interval is the gene's LOEUF score, 0.92, which puts it in group 3 of 6, group 1 being the genes least tolerant of losing a copy. Missense variants: 340 observed, 374.06 expected, observed/expected ratio (o/e) 0.91, 90% interval 0.83 to 0.99. Synonymous variants: 141 observed, 155.14 expected, observed/expected ratio (o/e) 0.91, 90% interval 0.79 to 1.04.
Gene-disease validity (ClinGen):
ClinGen rates the evidence that SAG causes each of these diseases.
retinitis pigmentosa 47 (autosomal recessive): Definitive.
Homologues: Orthologues: chimpanzee SAG (99% identical), macaque SAG (98% identical), dog SAG (89% identical), rat Sag (89% identical), mouse Sag (87% identical), guinea pig SAG (86% identical), pig SAG (85% identical), rabbit SAG (72% identical), tropical clawed frog sag (65% identical), zebrafish saga (53% identical), zebrafish sagb (53% identical), Drosophila melanogaster krz (46% identical), and 1 more. Paralogues in human: ARRB1 (56% identical), ARRB2 (53% identical), ARR3 (47% identical).
Diseases named in the same sentence as SAG in open-access papers:
SAG is named in the same sentence as 91 diseases in open-access papers, as found by Europe PMC text mining. Sharing a sentence is not in itself a finding about the gene and the disease. The quoted sentences say what the papers report.
Oguchi disease (13 papers, 2012 to 2025). Oguchi disease is an autosomal recessive retinal disorder characterized by congenital stationary night blindness and the Mizuo-Nakamura phenomenon. "SAG gene mutations were confirmed in all four of our enrolled patients diagnosed with Oguchi disease." (PMID 35549688, 2022). "The identification of the novel canonical splice site SAG gene variant in three members of the same family with clinically confirmed Oguchi disease reinforces its pathogenicity." (PMID 35549688, 2022). "On the other hand, GRK1 gene mutations are mostly found in southern Asians and Europeans patients with Oguchi disease, with very few reports of families harboring SAG gene mutations." (PMID 35549688, 2022). "It has been reported that SAG mutations not only cause the typical form of Oguchi disease, but also cause retinitis pigmentosa." (PMID 35246075, 2022). "Oguchi disease-1 is caused by homozygous or heterozygous mutations in the SAG gene, which is located on chromosome 2q37.1." (PMID 35246075, 2022). "Among the mutations related to Oguchi disease in SAG gene are; a gross deletion of 3224 bp including exon 2, a small deletion of one nucleotide in codon 309, and around 5 missense/nonsense mutations." (PMID 35549688, 2022). "Oguchi disease has been found to be associated with gene mutations in SAG and GRK1, which are vital factors in the recovery phase of phototransduction after light stimuli." (PMID 35246075, 2022). "As most of our knowledge of Oguchi disease stems from our understanding of loss of SAG function further research is required to better understand GRK1‐related Oguchi disease." (PMID 33252155, 2021). "Previous studies have revealed that mutations in the Arrestin 1 gene (Arr 1, also abbreviated as SAG, soluble antigen) cause Oguchi disease, a type of autosomal recessive “stationary” night blindness or autosomal recessive RP." (PMID 31781647, 2019). "The SAG mutation in human Oguchi disease is also causally associated with a discoloration of the fundus, termed the Mizuo-Nakamura phenomenon." (PMID 24019744, 2013). "Conversely, and more in line with our results, mutations in the SAG gene have been associated with Oguchi disease, a variant of retinitis pigmentosa." (PMID 24040246, 2013). "We report here a novel homozygous nonsense mutation in SAG in an individual with Oguchi disease and multiple neurologic and hematological disorders." (PMID 22665972, 2012). "Our findings have expanded the spectrum of Oguchi disease associated mutations in SAG gene and may serve as a basis for genetic diagnosis for Oguchi disease." (PMID 35549688, 2022). "We report a case of Oguchi disease with novel heterozygous mutations in SAG." (PMID 35246075, 2022). "Oguchi disease is associated with bi‐allelic pathogenic variants in GRK1 or SAG." (PMID 35612091, 2022). "Indeed, SAG mutations are concentrated in Japanese patients of Oguchi disease while GRK1 mutations are very rarely reported in Japanese patients." (PMID 35549688, 2022). "Mutations in the non-coding region of SAG gene may play a role in the pathogenesis of Oguchi disease, so should be considered in genetic testing of Oguchi disease patients." (PMID 35549688, 2022). "In human populations, SAG mutations have previously been associated with Oguchi disease and RP." (PMID 24019744, 2013). "Oguchi disease has been shown to be the most frequent cause of congenital stationary night blindness in the Japanese population, where the disease is frequently caused by only a single base pair deletion (c.926delA; p.N309Tfs*12) in SAG." (PMID 22665972, 2012). "In addition a mutation in SAG has been described previously as causing Oguchi disease in an Indian family." (PMID 22665972, 2012). "SAG gene variants may be the underlying genetic cause for Oguchi disease in Egypt." (PMID 35549688, 2022). "Another noteworthy finding is a homozygous nonsense mutation in the SAG gene in patient MOL2008-1, leading to Oguchi disease." (PMID 39062705, 2024).
Oguchi disease (continued). "For example both SAG and GRK1 in addition to an association with PRC thickness have a known involvement in Oguchi disease, a rare autosomal eye condition which causes visual impairment." (PMID 36848389, 2023). "Compound heterozygous variations in the SAG gene were detected in a Chinese family clinically diagnosed as Oguchi disease, whereas another showed homozygous variation." (PMID 35549688, 2022). "No studies reported any patients with Oguchi disease in Egyptian or African population, and it remained unclear whether they harbor SAG gene or GRK1 gene mutations." (PMID 35549688, 2022). "Oguchi disease has not been described so far in the Egyptian population or in any African population, and the mutation spectrum remains unknown whether SAG or GRK1 mutations will prevail." (PMID 35549688, 2022). "However, to date no SAG mutations have been shown to cause Oguchi disease in Pakistani patients." (PMID 22665972, 2012).
breast cancer (7 papers, 2002 to 2022). A primary or metastatic malignant neoplasm involving the breast. "In the present study, we endeavored to pool public genomic data to assess the association between SAG expression and prognosis in breast cancer." (PMID 31926110, 2020). "In the present study, we revealed that SAG gene expression is upregulated in breast cancer cells and that SAG overexpression is associated with significant poorer survival in breast cancer, especially the luminal A subtype." (PMID 31926110, 2020). "In addition, we provide evidence that SAG exerts a pro-proliferative effect in breast cancer cells and that its overexpression is associated with unfavorable prognosis in breast cancer." (PMID 31926110, 2020). "MMTV SAg is highly expressed in MMTV-associated human breast cancer and may have a similar role in humans as it does in the mouse." (PMID 29404275, 2018). "Because SAG is regarded as an oncoprotein and significantly associated with poor prognosis for several human cancers, we also used bc-GenExMiner to investigate whether SAG overexpression was associated with survival of breast cancer patients." (PMID 31926110, 2020). "MMTV SAg is highly expressed in MMTV positive human breast cancer, and it appears to play a similar role in humans as it does in mice." (PMID 35458452, 2022). "In the present study, however, we showed that levels of SAG mRNA are significantly higher in breast cancer tissues than in normal breast-like tissues and that increased SAG expression is associated with the ER and HER2 expression status of breast cancer." (PMID 31926110, 2020). "Using bc-GenEx-Miner 4.3, we first analyzed the SAG expression profile across different breast cancer subtypes." (PMID 31926110, 2020). "Using the cBioPortal for Cancer Genomics with breast cancer data from The Cancer Genome Atlas (TCGA) database, 10 candidate genes were identified that positively correlated with SAG expression." (PMID 31926110, 2020). "The Kaplan-Meier curves showed that higher SAG expression correlated with poorer survival in breast cancer." (PMID 31926110, 2020). "In the present study, we found that COPB2 is upregulated along with SAG in breast cancers and that both are highly expressed in breast cancer cell lines." (PMID 31926110, 2020). "Conversely, ectopic overexpression of SAG in SKBR-3 or T47d breast cancer cells enhanced the cells’ proliferative potential." (PMID 31926110, 2020). "The heat map generated using the UCSC Xena browser confirmed that SAG is highly co-upregulated with COPB2 in breast cancers." (PMID 31926110, 2020). "To further clarify the relationship between SAG and COPB2, we used the CBioPortal to examine the RNAseq data in a breast cancer cohort and showed that SAG is co-upregulated with COPB2." (PMID 31926110, 2020). "As expected, SAG expression was significantly higher in breast cancer tissues than in normal breast-like tissues." (PMID 31926110, 2020). "We found that SAG or COPB2 knockdown significantly inhibited breast cancer cell migration and invasion as compared to the control group, while ectopic overexpression of SAG slightly enhanced breast cancer cell migration and invasion." (PMID 31926110, 2020). "We also observed that COPB2 is highly upregulated along with SAG in breast cancers." (PMID 31926110, 2020). "Moreover, COPB2 knockdown abolished SAG-induced breast cancer cell proliferation and invasion, which strongly suggests COPB2 signaling is involved in the mechanism underlying the oncogenic effect of SAG." (PMID 31926110, 2020). "As expected, knocking down SAG or COPB2 inhibited breast cancer cell proliferation." (PMID 31926110, 2020). "Our findings suggest that levels of SAG and COPB2 expression may be useful prognostic indicators in breast cancers and that SAG may be involved in COPB2-related signaling during breast cancer development." (PMID 31926110, 2020).
breast cancer (continued). "Our findings show that SAG is associated with poorer survival in breast cancer, especially the luminal A subtype, and that there is highly correlated co-overexpression of SAG and COPB2 in breast cancers." (PMID 31926110, 2020). "Given the apparent involvement of SAG in malignant behavior of breast cancer, we next investigated the signaling pathways in which SAG may be involved." (PMID 31926110, 2020). "Moreover, SAG may be involved in a COPB2-related signaling pathway that plays an oncogenic role in breast cancer." (PMID 31926110, 2020). "While the DBA/2 derived Eb T lymphoma cells did not express this SAG, the spontaneous metastatic variant ESb and its adhesion variant ESb-MP expressed endogenous mouse mammary tumour provirus (Mtv)- typical intracisternal A-particles (IAP), Mtv7 orf/SAG message and vSAG7 protein at the cell surface." (PMID 11875749, 2002). "To further evaluate the oncogenic effects of SAG and COPB2 in breast cancer cells, we performed a set of transwell migration and invasion assays." (PMID 31926110, 2020). "We then used RT-qPCR to measure the relative levels of SAG and COPB2 expression in three breast cancer cell lines (MCF-7, SKBR-3 and T47d) and in a normal breast cell line (MCF-10A)." (PMID 31926110, 2020). "We found that gene expression of both SAG and COPB2 was higher in all three breast cancer cell lines than in normal breast tissue cells." (PMID 31926110, 2020). "Subsequent in vitro experiments demonstrated that SAG and COPB2 act cooperatively to stimulate breast cancer cell proliferation, migration and invasion." (PMID 31926110, 2020). "Because both SAG and COPB2 exert pro-proliferative effects in several human cancers, we wanted to determinate how SAG and COPB2 knockdown influenced breast cancer cell proliferation, and whether SAG and COPB2 acted cooperatively to affect cell proliferation." (PMID 31926110, 2020). "We also detected highly correlated co-overexpression of SAG and COPB2 in breast cancers." (PMID 31926110, 2020). "Taken together, our findings indicate that expression of SAG and COPB2 may be a useful prognostic indicator in breast cancer." (PMID 31926110, 2020). "Moreover, this relationship between SAG and COPB2 was most significant in luminal B breast cancers." (PMID 31926110, 2020). "By contrast, to our knowledge there have been no studies examining SAG’s actions in breast cancer." (PMID 31926110, 2020).
lung carcinoma (7 papers, 2012 to 2023). "Conversely, SAG is reportedly overexpressed in primary colon carcinomas and prostate cancers, and an association between SAG overexpression and poor survival has been reported in lung cancers." (PMID 31926110, 2020). "In lung cancer, it is known that SAG acts as an onco-cooperating gene required for tumorigenesis induced by a mutant Kras, that it is significantly overexpressed in lung cancer tissues, and that its expression correlates with poor patient prognosis." (PMID 31926110, 2020). "Knocking down SAG inhibits lung cancer cell proliferation, in vitro and in vivo, and contributes to the recovery of radiation sensitivity in radiation-resistant cancer cells." (PMID 31926110, 2020). "We next determined the effect of transfected SAG/CUL5 or RBX1/CUL1 on endogenous levels of β-TrCP1 in two lung cancer cell lines, A427 and A549 harboring relatively high levels of β-TrCP1." (PMID 27910872, 2016). "The endogenous binding of these E2–E3 pairs was further confirmed in two lung cancer cell lines under physiological unstressed conditions in a pull-down assay using antibody against either SAG or RBX1 or antibodies against each of four E2s." (PMID 27910872, 2016). "In human tissues, SAG overexpression was detected in carcinomas of lung, colon, stomach, cervix and liver, with poor survival of lung cancer patients." (PMID 27955654, 2016). "Expression analysis reveals that hypoxia induced lung cancer related biomarkers, HIF and its modulating proteins (TGM2, CSNK1A1, CTNNA1, NAMPT/Visfatin, TNFRSF1A, ETS1, SRC-1, FN1, APLP2, DMBT1/SAG, AIB1 and AZIN1) are significantly down regulated." (PMID 23122428, 2012). "Following this lead, we determined the levels of SAG and RBX1 in comparison with those of three F-box proteins in multiple lung cancer cell lines and found in general that the levels of SAG, but not of its family member RBX1, is correlated in an inverse manner with the levels of β-TrCP1 only." (PMID 27910872, 2016). "While overexpression of SAG, but not of RBX1, is associated with poor survival of lung cancer patients, SAG expression is required to lung tumorigenesis triggered by Kras mutation." (PMID 27955654, 2016).
congenital stationary night blindness (6 papers, 2012 to 2023). "Mutations in SAG, the gene coding for arrestin-1, have been shown to cause RP by causing the rod cell’s dysfunction in returning to its dark state and, therefore, preventing further phototransduction, which can cause both IRD and congenital stationary night blindness (CSNB)." (PMID 36830640, 2023). "Six genes encoding major components of the phototransduction cascade (RHO, GNAT1, PDE6B, GRK1, and SAG) and the regeneration of the visual pigment (RDH5) are described in congenital stationary night blindness (CSNB) patients." (PMID 24760071, 2014).
hepatocellular carcinoma (5 papers, 2015 to 2025). A malignant tumor that arises from hepatocytes. "Conversely, patients who achieve sAg loss following antiviral treatment always have a satisfactory off-treatment response and a low incidence of hepatocellular carcinoma." (PMID 34721439, 2021). "In addition, although 9/11 of HCCs are HBV positive, we found that the two hepatoma cases with ‘unknown’ etiology also showed the involvement of SAG-UPS in progressive malignant transformation of liver cancer, hence suggesting the ubiquitous nature of SAG-UPS in cancer progression." (PMID 27551463, 2015).
liver cancer (5 papers, 2015 to 2025). An epithelial or non-epithelial malignant neoplasm that arises from the liver. "Interestingly, we found that SARM expression is increased at the later stages of liver cancer, suggesting that the reciprocal relationship of SAG/SARM expression may be associated with the progression of hepatocarcinogenesis." (PMID 27551463, 2015). "Here, we investigated the molecular mechanism by which SAG-UPS regulates death/survival of liver cancer cells." (PMID 27551463, 2015). "To affirm the relationship between SAG expression and the intrinsic apoptotic potency in liver cancer, we tested the release of cytochrome c in SAG-knockdown HCC cells." (PMID 27551463, 2015). "Furthermore, Noxa and SARM, which are functional proapoptotic factors in liver cancer, are regulated by SAG-UPS." (PMID 27551463, 2015). "Furthermore, based on our observations here and in previous findings, it is conceivable, from the early increase in SAG expression, that SAG initiates and promotes liver cancer, probably by downregulating Noxa and SARM via protein degradation." (PMID 27551463, 2015). "To elucidate how SAG-UPS regulates Noxa and SARM in liver cancer, we characterized six different human HCC cell lines for their expression profiles of apoptotic factors under various stimulatory challenges." (PMID 27551463, 2015). "Here, the authors showed that SAG-UPS degrades pro-apoptotic signaling factors, thus conferring antiapoptosis and uncontrolled cell survival strategy, which explains the promotion of liver cancer." (PMID 26492374, 2015). "Our findings provide novel insights into how SAG-UPS confers antiapoptosis strategy, and deregulates cell death /survival, in a protumorigenic microenvironment that promotes liver cancer progression." (PMID 27551463, 2015). "Overall, our results indicate reciprocal expression profiles between SAG/Noxa and SAG/SARM in primary HCC, suggesting that SAG might regulate liver cancer progression by opposing the roles of Noxa and SARM." (PMID 27551463, 2015). "Importantly, under unstressed physiological condition, endogenous SAG bound to endogenous RHEB, but neither SAG nor RHEB binds to UBE2F or mTOR in these liver cancer cell lines." (PMID 39762645, 2025).